ZDBF2 (zinc finger DBF-type containing 2)
Synonyms: KIAA1571; FLJ45338
Tractability: PROTAC: ubiquitination databases record sites on it.
Gene: Protein-coding gene on chromosome 2 (206,274,657 to 206,314,437, forward strand). Ensembl gene ENSG00000204186.
Subcellular location (Human Protein Atlas): Nucleoplasm; Cytosol
Gene Ontology:
Molecular function: nucleic acid binding; zinc ion binding
Biological process: genomic imprinting
Genetic constraint (gnomAD): Loss-of-function variants: 5 observed, 7.46 expected, observed/expected ratio (o/e) 0.67, 90% interval 0.35 to 1.4. That is too few expected variants to judge how well the gene tolerates losing a copy. Missense variants: 2,675 observed, 2,875.9 expected, observed/expected ratio (o/e) 0.93, 90% interval 0.9 to 0.96. Synonymous variants: 894 observed, 990.18 expected, observed/expected ratio (o/e) 0.9, 90% interval 0.85 to 0.95.
Homologues: Orthologues: chimpanzee ZDBF2 (99% identical), macaque ZDBF2 (92% identical), pig ZDBF2 (59% identical), dog ZDBF2 (58% identical), rat Zdbf2 (46% identical), mouse Zdbf2 (45% identical).
Diseases named in the same sentence as ZDBF2 in open-access papers:
ZDBF2 is named in the same sentence as 10 diseases in open-access papers, as found by Europe PMC text mining. Sharing a sentence is not in itself a finding about the gene and the disease. The quoted sentences say what the papers report.
Beckwith-Wiedemann syndrome (1 paper, 2022). Beckwith-Wiedemann syndrome (BWS) is a genetic disorder characterized by overgrowth, tumor predisposition and congenital malformations. "However, studies have shown that aberrant hypermethylation of the maternal Zdbf2-DMR has been observed in some patients with Beckwith-Wiedemann Syndrome, an imprinting disorder characterized by body overgrowth and enlargement of internal organs." (PMID 35988119, 2022).
dwarfism (1 paper, 2022). "Additionally, the Zdbf2 growth reduction diverges from GH-related dwarfism: Gh-deficient mice grow normally until 10dpp, after which only they exhibit general growth impairment with reduced levels of circulating IGF-1." (PMID 35049495, 2022).
Globozoospermia (1 paper, 2015). Any structural anomaly of the acrosome resulting in a round sperm head. "Six imprinted genes showed different 5hmC patterns between normal and abnormal sperm (GDAP1L1, GNAS, KCNK9, LIN28B, RB1, RTL1), and five imprinted genes showed different 5hmC patterns between normal and globozoospermia sperm (KCNK9, LIN28B, RB1, SLC22A18, ZDBF2)." (PMID 25762640, 2015).
sarcopenia (1 paper, 2025). Progressive decline in muscle mass due to aging which results in decreased functional capacity of muscles. "Experimental validation confirmed significant upregulation of USP54, CHAD, and ZDBF2 in aging muscles, and functional analysis revealed enrichment of signaling pathways related to bone development, immune response, and apoptosis, consistent with known mechanisms of sarcopenia." (PMID 41303670, 2025).
Temple syndrome (1 paper, 2019). "A similar gain of iDMR methylation associated with an elevated mRNA level of ZDBF2 was reported for a case of Temple syndrome." (PMID 31564644, 2019).
cancer (4 papers, 2012 to 2024). A tumor composed of atypical neoplastic, often pleomorphic cells that invade other tissues. "Also, for other genes featuring a combination of downregulation and LOI in cancer, e.g., for ZDBF2 and ZNF331, also observed in cancer cells in this study, incorrect transcript usage should be further explored." (PMID 39766305, 2024). "The numbers of cancer tissue cases with hypermethylation above the range of the methylation rates in the normal ovarian surface epithelium were 17 for H19, 21 for GTL2, 21 for ZDBF2, and 14 for PEG1." (PMID 22443985, 2012). "According to GEO database (GSE145608), hsa_circ_0002141, a circRNA originated from zinc finger DBF-type containing 2 (ZDBF2) (namely circZDBF2), was discovered to be with high expression in OSCC tissues, while it has not been investigated in cancer developmental present, let alone in OSCC." (PMID 35365168, 2022).
tumor (3 papers, 2012 to 2025). "As for the mutation in ZDBF2 gene, the variant allele frequency was more than 0.15 in all tumor samples." (PMID 40046420, 2025). "When taking into account the different tumour subtypes, we detected 24 SNPs (in eight genes: ZDBF2, PEG10, MEST, H19, IGF2, MEG3, ZNF331 and HM13) exhibiting DI in at least one subtype compared to the normal tissue samples." (PMID 30297886, 2018).
ZDBF2 also shares sentences with these, for which no sentence is quoted: Intellectual disability (1 paper); intestinal T-cell lymphoma (1); intrauterine growth restriction (1).